ELOVL5 (ELOVL fatty acid elongase 5)
Diseases named in the same sentence as ELOVL5 in open-access papers (continued):
Sharing a sentence is not in itself a finding about the gene and the disease.
cancer (21 papers, 2016 to 2025). A tumor composed of atypical neoplastic, often pleomorphic cells that invade other tissues. "ELOVL5 has also been shown to be related to cancer, and estrogen exposure in MCF-7 cells has been linked to its up-regulation." (PMID 40770488, 2025). "ELOVL5 expression is associated with the levels of cellular arachidonic acid and adrenic acid (C22:4, ω-6) in cancer cells, which are subjected to lipid peroxidation and ferroptosis." (PMID 36970499, 2023). "In patients with ER+ cancer, low Elovl5 mRNA expression was associated with a worse OS prognosis compared to patients with high Elovl5 expression." (PMID 36056008, 2022). "ELOVL5 participates directly in the elongation of polyunsaturated fatty acids (PUFAs) that are considered to play an important role in cancer cell metabolism." (PMID 36714261, 2023). "However, the use of DGAT inhibitors might also improve the efficacy of anti-cancer drugs for the treatment of patients with a high risk of metastases associated to low levels of Elovl5 by suppressing the resistance or buffering of these anti-cancer drugs by LD." (PMID 36056008, 2022). "Additionally, research has shown the upregulation of other PUFA synthesis enzymes in cancer cells, such as elongation of very long-chain fatty acid protein 5 (ELOVL5) and fatty acid desaturase 1 (FADS1)." (PMID 40709182, 2025). "Therefore, changes in the expression of ELOVL5 in cancer cells would change the VL-PUFA profile and affect the proliferation and progression of cancer cells." (PMID 36970499, 2023). "As the ferroptosis pathway is a possible target for cancer treatment, ELOVL5 could be a marker for determining whether ferroptosis-mediated treatment is applicable." (PMID 36970499, 2023). "The findings suggest the involvement of ELOVL5 in cancer cell proliferation and invasion, although its effects and mechanisms remain unclear." (PMID 36970499, 2023). "Furthermore, we evaluated the expression of Diacylglycerol Acyltransferases (DGAT) 1 and 2 which participate in TAG synthesis, and found an increase in DGAT1 and DGAT2 expression in Elovl5-silenced cancer cells." (PMID 36056008, 2022). "The analyses of RNA-seq data of LNCaP/AR and LNCaP/AR-shp53/shRB revealed that ELOVL5 was upregulated in NE-like enzalutamide resistant LNCaP/AR-shp53/shRB cells compared to LNCaP/AR cells, which was further confirmed by RT-qPCR and the expression pattern in different cancer tissues." (PMID 34439125, 2021). "Higher FPKM values for FADS1, ELOVL5, and ACLY were detected in cancer tissues than in adjacent normal tissues (P < 0.01; P < 0.01; P < 0.01), suggesting that alterations in lipid metabolism in ESCC are mediated by altered expression of these genes." (PMID 41184824, 2025). "This is also reflected by the correlation (ELOVL5, FADS2 and ACSL4) and anti-correlation (FASN and SCD) of these enzymes with Zeb1 expression in cancer cell lines." (PMID 39009641, 2024). "Genome analysis has demonstrated increased expression of ELOVL5 in human CRC and other types of cancers, including breast, prostate, and kidney cancers." (PMID 36970499, 2023). "The enzymes in the VL-PUFA synthesis pathway, including ELOVL5, FADS2, and HSD17B12, can affect cellular arachidonic acid level and PGE2 level, and thus could change the biological activities of cancer cells in multiple stages." (PMID 36970499, 2023). "The mRNA levels of ELOVL4, ELOVL5 and FADS2 were increased in cultured cancer cells comparing to normal colon cells, but we did not detected the expression of ELOVL2 and FADS1 in these cells." (PMID 32029824, 2020).
cardiovascular diseases (1 paper, 2020). "The current work found the presence of private alleles of ELOVL5, which could be directly related to the %BF and the risk of cardiovascular diseases in females." (PMID 33158152, 2020).
infection (1 paper, 2021). The state of being infected such as from the introduction of a foreign agent such as serum, vaccine, antigenic substance or organism. "The inverse regulation of Fads1/Elovl5, compared to Fasn/Fads2, at 6hr post infection with Mtb was surprising since all genes are targets of the LXR and SREBP1 regulators of FA metabolism." (PMID 34951591, 2021). "Fads1 and Elovl5 transcript levels were transiently repressed at 6hr post infection with Mtb, while on the opposite those of Fads2 were increased from 6hr until 24hr." (PMID 34951591, 2021).
ELOVL5 also shares sentences with these, for which no sentence is quoted: cerebellar ataxia (3 papers); colorectal cancer (3); ovarian carcinoma (2); peripheral neuropathy (2); -phosphoglycerate dehydrogenase deficiency (1); 3-methylglutaconyl-CoA hydratase deficiency (1); abetalipoproteinemia (1); Atrophy (1); brain disease (1); breast (1); cervical cancer (1); chronic kidney disease (1); clear cell renal cell carcinoma (1); coproporphyria (1); endometriosis (1); esophageal cancer (1); female infertility (1); Gait ataxia (1); lung carcinoma (1); lymph node metastasis (1); metabolic disease (1); mood disorder (1); multiple system atrophy of cerebellar type (1); muscular dystrophy (1); non-small cell lung carcinoma (1); Nystagmus (1); of the colon (1); osteosarcoma (1); ovarian tumor (1); pancreatic cancer (1).
A further 10 diseases each share a sentence with ELOVL5 in 1 paper.